OPA1 (OPA1 mitochondrial dynamin like GTPase)
Diseases named in the same sentence as OPA1 in open-access papers (continued):
Sharing a sentence is not in itself a finding about the gene and the disease.
optic atrophy (continued). "Additional genetic testing, using an “optic atrophy sequencing panel,” was positive for two variants in his OPA1 gene: c.2287del (p.Ser763Valfs*15) NM_130837.2 and c.1311A>G (p.lIle437Met) NM_130837.2." (PMID 35741767, 2022). "Biallelic pathogenic variants in OPA1 are associated with Behr syndrome, an autosomal recessive disorder characterized by early-onset optic atrophy along with ataxia, pyramidal signs, and intellectual disability." (PMID 35736332, 2022). "Homozygous or compound heterozygous pathogenic variants in the OPA1 gene lead to Behr syndrome, which refers to a combination of early onset optic atrophy and neurological signs such as ataxia, peripheral neuropathy and pyramidal signs." (PMID 35328032, 2022). "In contrast, her son had early-onset severe optic atrophy because he was a constitutional heterozygous carrier of the pathogenic OPA1 variant." (PMID 35328032, 2022). "We ruled out the presence of the p.Arg445His missense pathogenic variant in the OPA1 gene in all family members by Sanger sequencing as OPA1 pathogenic variants are the most frequent genetic cause behind optic atrophy associated with deafness." (PMID 36330437, 2022). "The mother had subclinical optic atrophy due to a postzygotic mosaic of a pathogenic variant in the OPA1 gene." (PMID 35328032, 2022). "Seven patients out of 33 sporadic HSPs (21.2%) received a genetic diagnosis: five harbored mutations in SPAST, one case had biallelic variants in SPG7, and a young woman manifesting with HSP + early onset optic atrophy harbored a nonsense variant in OPA1." (PMID 33669240, 2021). "In the majority of cases, OPA1 dominant mutations cause exclusively optic atrophy as clinical manifestation." (PMID 33806088, 2021). "Cheetham and colleagues describe an efficient CRISPR-Cas9 gene editing strategy to correct a variant in the nuclear gene OPA1 in dominant optic atrophy patient-derived iPSCs." (PMID 34589289, 2021). "In the last years, thanks to next generation sequencing (NGS), novel genes have been found associated with optic atrophy, many of which modulating OPA1 activity, i.e., AFG3L2 and YME1L." (PMID 33806088, 2021). "With the same OPA1 disease-causing variant, one patient had severe optic atrophy with best-corrected visual acuity of 20/2000, but another patient was asymptomatic." (PMID 34573359, 2021). "In one large family, the optic atrophy resembled the DOA “plus” phenotype related to OPA1 mutations, showing neuropathy and mitochondrial myopathy in adult life." (PMID 33578638, 2021). "In support of our results, a mouse model of optic atrophy harboring the homologous sequence alteration in the mouse Opa1 gene showed similar mutation-induced effects on transcript and protein levels." (PMID 34853716, 2021). "As an example, expression of a the MGM1-OPA1 chimeric construct was used to model both dominant and recessive human pathological mutations in OPA1, associated to optic atrophy (DOA), to DOA+ and to pathologies associated to mtDNA depletion." (PMID 33672627, 2021). "The patients have an optic atrophy with a clinical presentation similar to OPA1 mutations, but also a specific clinical feature that consists of a singular foveopathy never, to our knowledge, described in any mitochondriopathy or optic neuropathy." (PMID 31550237, 2020). "Variants in YME1L alter OPA1 processing, which induces imbalance between fission and fusion with the phenotype of optic atrophy." (PMID 33426505, 2020). "In two other optic atrophy studies, the OPA1 variant p.(Ile382Met) was identified in a compound heterozygous state in a total of five cases, and heterozygous carriers were an asymptomatic father and a mother with myopia and mild sensorineural hearing loss." (PMID 32040484, 2020). "Certain human mutations in mitofusin 2 (MFN2) and optic atrophy protein 1 (OPA1) cause disease phenotypes, such as peripheral neuropathy and optic atrophy, which are often also associated with mtDNA depletion." (PMID 31170154, 2019).
optic atrophy (continued). "A novel OPA1 variant was identified in one case who suffered auditory neuropathy with optic atrophy." (PMID 31427586, 2019). "This is further supported by the close association of mutations in MFN2 and OPA1 with Charcot–Marie–Tooth disease and optic atrophy, respectively, while disease as a direct consequence of DRP1 mutation occurs far less frequently." (PMID 30840087, 2019). "Dominant mutations have been reported in OPA1, and associated with optic atrophy, the most common hereditary optic neuropathy." (PMID 30030364, 2018). "Defective mitochondrial function attributed to optic atrophy 1 (OPA1) mutations causes primarily optic atrophy and, less commonly, neurodegenerative syndromes." (PMID 29604226, 2018). "Instead, recessive mutations in OPA1 cause Behr syndrome, a complex neurological disorder characterized by early-onset optic atrophy, ataxia, spasticity and mental retardation." (PMID 30030364, 2018). "This associates with increased processing of the dynamin-like GTPase optic atrophy 1 (OPA1), whose ablation is a direct cause of inherited optic atrophy." (PMID 29867190, 2018). "Few cases harboring compound heterozygous OPA1 mutations have been described manifesting complex neurodegenerative disorders in addition to optic atrophy." (PMID 28494813, 2017). "The association of optic atrophy with spastic paraplegia, resembling cases that fit the historical description of Behr syndrome, has been well described in several unrelated OPA1 mutation carriers." (PMID 27696015, 2016). "Similar to Harding disease in LHON, OPA1 mutation carriers can also develop an MS-like illness where the optic atrophy occurs on the background of a more disseminated inflammatory process with neuroradiological and serological features, consistent with MS." (PMID 27696015, 2016). "In this study, iPSCs were obtained from patients carrying an OPA1 mutation (OPA1+/−-iPSC) that were diagnosed with optic atrophy." (PMID 26738566, 2016). "Taken together, these results suggest that the primary pathogenesis of optic atrophy due to an OPA1 mutation is most likely due to a reduced number of RGCs, secondary to increased levels of RGC apoptosis." (PMID 26738566, 2016). "In the present study, we were able to generate human iPSCs from fibroblast cells obtained from patients diagnosed with optic atrophy and carrying an OPA1 mutation." (PMID 26738566, 2016). "Mutations in MFN2 have been recently disclosed in familial multisystemic disorder with optic atrophy beginning in early childhood, associated with axonal neuropathy and mitochondrial myopathy in adult life, a presentation resembling OPA1 plus phenotype." (PMID 26251896, 2015). "Analysis of the family members in the two sporadic cases demonstrated that one parent in each of the two families had the OPA1 mutation and mild phenotype of optic atrophy." (PMID 23401657, 2013). "As human patients with OPA1 mutations develop optic atrophy, we took a closer look at eye development." (PMID 23516612, 2013). "The presence of multiple deletions in the mtDNA has been found in the skeletal muscle of the majority of patients harbouring OPA1 mutations, even in those with isolated optic atrophy." (PMID 22776096, 2012). "It is therefore very revealing that in two family members with optic atrophy and hearing loss due to a pathogenic OPA1 mutation, auditory investigations localised the defect to the terminal unmyelinated portions of cochlear nerve." (PMID 21112411, 2011). "The systematic search for OPA1 mutations should therefore prove useful in unexplained and atypical cases of optic atrophy." (PMID 19325939, 2009). "In skeletal muscle of optic atrophy patients, mutation of OPA1 causes mitochondrial myopathy characterized by cytochrome c oxidase negative, ragged red fibers and abnormal morphology and distribution of mitochondria." (PMID 19718456, 2009).
optic atrophy (continued). "Our case shows that OPA1 analysis can be useful in late-onset cases of ADOA when the main secondary causes of optic atrophies have been excluded." (PMID 19325939, 2009). "We performed DNA sequencing of the entire coding sequence and the exon/intron junctions of the OPA1 gene, and we searched for the mitochondrial DNA mutations responsible for Leber hereditary optic atrophy by sequencing entirely mitochondrial DNA." (PMID 19325939, 2009). "From the literature, among the cases of optic atrophy caused by OPA1, 84.31% (591/701) presented as non-syndromic optic atrophy (involving visual symptoms only), a rate that surpasses that of ACO2 (71.08%) but falls below DNAJC30 (which exhibits complete prevalence, 100%)." (PMID 39423307, 2025). "Moreover, OPA1 is associated not only with SNHL but also with optic atrophy and peripheral neuropathy, leading to progressive vision loss, sensory loss, and muscle weakness." (PMID 40268851, 2025). "A fission yeast msp1 mutant, which is defective in dynamin GTPase, required for mitochondrial fusion and mitochondrial DNA maintenance, has been employed to screen repurposed drugs for a potential remedy for optic atrophy caused by mutations in OPA1, the human orthologue of msp1." (PMID 37859837, 2023). "In addition, variants in OPA1 were observed to be major causes of optic atrophy in our cohort, accounting for 38.9% of our solved cases." (PMID 36071901, 2022). "All seven cases of optic atrophy with variants in OPA1 were non-syndromic." (PMID 36071901, 2022). "He presented with congenital nystagmus, progressive vision loss, and optic atrophy, as well as progressive ataxia, and was found to have two likely pathogenic variants in his OPA1 gene: c.2287del (p.Ser763Valfs*15) maternally inherited and c.1311A>G (p.lIle437Met) paternally inherited." (PMID 35741767, 2022). "We report on a patient with DOA + manifesting as bilateral optic atrophy, spastic paraparesis, urinary incontinence and white matter changes in the central nervous system associated with a novel heterozygous splice variant NM_015560.2(OPA1):c.2356-1 G > T." (PMID 35534703, 2022). "However, optic atrophy plus syndrome is more frequent with a missense mutation in OPA1 gene, while classic optic atrophy is mostly associated with deletion." (PMID 34440452, 2021). "Besides these complex and severe disorders, dominant DRP1 mutations are also the cause of isolated optic atrophy undistinguishable from OPA1-DOA, as described by Gerber and colleagues." (PMID 33806088, 2021). "Other iPSC lines were generated from fibroblasts obtained from patients with an optic atrophy “plus” phenotype: one carrying the mutation c.1861C>T; p.Gln621Ter in OPA1 and the other one harboring the mutation c.1635C>A; p.Ser545Arg in OPA1, both of them in heterozygosis." (PMID 33477675, 2021). "Likewise, fibroblasts from patients diagnosed with optic atrophy, carrying an intronic mutation in OPA1 (intron 24 c.2496+1G>T), were reprogrammed into the iPSCs." (PMID 33477675, 2021). "Optic atrophy and hearing impairment are the most prevalent clinical features associated with mutations in the OPA1 gene, but the function of OPA1 in hearing is still unknown." (PMID 34621753, 2021). "In addition, homozygous mutations in YME1L1 (MIM#617302), which also disrupt OPA1 processing have been identified in individuals with optic atrophy and mitochondrial disorders." (PMID 33632269, 2021). "Our results suggest that the p.D438G mutation in OPA1 causes optic atrophy in this family." (PMID 31781369, 2019). "Finally, the first homozygous OPA1 mutation has just been reported, associated with fatal infantile mitochondrial encephalomyopathy, hypertrophic cardiomyopathy and optic atrophy." (PMID 28494813, 2017).
optic atrophy (continued). "Infantile lethal outcome due to OPA1 mutations has been described for the first time very recently: a homozygous OPA1 mutation has been found in two sisters with fatal infantile mitochondrial encephalomyopathy, hypertrophic cardiomyopathy and optic atrophy." (PMID 28494813, 2017). "More recently, a compound homozygous OPA1 mutation has been identified for the first time in two affected Jewish sisters from consanguineous parents who developed a fatal infantile encephalomyopathy with hypertrophic cardiomyopathy and optic atrophy." (PMID 27696015, 2016). "Taken together, these results indicate that 17β-estradiol can promote RGC development possibly through inhibition of apoptosis, and thus may serve as a potential therapeutic agent for OPA1 mutation-related optic atrophy." (PMID 26738566, 2016). "Our results suggest that apoptosis mediated by OPA1 mutations plays an important role in the pathogenesis of optic atrophy, and both noggin and β-estrogen may represent potential therapeutic agents for OPA1-related optic atrophy." (PMID 26738566, 2016). "OPA1 mutations identified in the 12 Chinese families with optic atrophy." (PMID 23401657, 2013). "One report of a Behr syndrome associating DOA to pyramidal signs, ataxia and mental retardation was linked to an OPA1 mutation and another report describing a severe neuromuscular phenotype associated to optic atrophy was described in two OPA1 compound heterozygote siblings." (PMID 22776096, 2012). "However, the OPA1 gene is ubiquitously expressed and recent studies have suggested that mutation of OPA1 results in complicated optic atrophy “plus” phenotypes." (PMID 19718456, 2009). "In humans, mutation of OPA1 causes retinal ganglion cell death and optic atrophy." (PMID 19718456, 2009). "The aim of the present report is to show that a clinical phenotype similar to that of late-onset Leber hereditary optic neuropathy may be linked to an OPA1 mutation." (PMID 19325939, 2009). "The increase of basal autophagy and mitophagy is a common theme in mitochondrial diseases, in particular in those with optic atrophy, as documented by others and our own studies of different mtDNA mutations affecting ND subunits of complex I, and OPA1-related syndromes." (PMID 35858578, 2022). "Additionally, the phenotypic spectrum of SLC25A46 expanded, including the severe infantile Leigh-like encephalopathy, but also severe congenital ponto-cerebellar hypoplasia and more recently optic atrophy and Parkinsonism, this latter case resembling some specific OPA1 mutations." (PMID 33806088, 2021). "Furthermore, our results can be relevant for other diseases as the understanding of Marf and Opa1 functions could reveal new pathways for Charcot-Marie-Tooth disease and optic atrophy, caused by MFN2 and OPA1 mutations, respectively." (PMID 34830014, 2021). "Interestingly, FDXR-associated optic neuropathy seems to be variable and may present similar to OPA1-associated optic atrophy, Wolfram syndrome, or LHON." (PMID 33938912, 2021). "In addition to DOA, OPA1 has been implicated also in biallelic froms of syndromic optic atrophy." (PMID 35008635, 2021). "Optic atrophy and/or neuropathy is often the predominant feature associated with either OPA1 mutations or Leber Hereditary Optic Neuropathy (LHON, MIM: 500001), and this is often due to one of three mtDNA point mutations." (PMID 31866046, 2020). "There is an overlap between OPA1 mutations and LHON, and LHON progresses to an end stage characterized by bilateral optic atrophy and central vision loss." (PMID 28081242, 2017). "However, both noggin and β-estrogen can rescue this phenotype, suggesting apoptosis mediated by OPA1 mutations plays an important role in the pathogenesis of optic atrophy, and noggin and β-estrogen could be potential therapeutic agents." (PMID 26738566, 2016).
optic atrophy (continued). "Interestingly, mutations in OPA1, although originally described in nonsyndromic hereditary optic neuropathy, have recently been reported to also cause a syndromic form of optic atrophy associated with sensorineural deafness, ataxia, and multiple mitochondrial DNA deletions." (PMID 20405026, 2010). "However, no further mutations were identified in a cohort of 48 patients with nonsyndromic optic atrophy (in whom mutations in optic atrophy 1 gene [OPA1] and the most frequent LHON mutations [mitochondrial DNA {mtDNA} G11778A, G3460A, T14484C, and G15257] had been excluded)." (PMID 20405026, 2010). "Leber hereditary optic neuropathy (LHON) mitochondrial mutations and mutations in the Optic atrophy-1 gene (OPA1) were excluded." (PMID 20069065, 2010). "Although this work led to a report associating the presenilin associated, rhomboid-like (PARL) gene with the LHON phenotype, the same linkage region harbors optic atrophy 1 (OPA1), a gene critical to mitochondrial function." (PMID 21203403, 2010). "In yeast overexpression systems, SLC25A46 interacts with mitofusin 2 (MFN2) and optic atrophy 1 (Opa1) genes which are associated with CMT2A (MFN2) and optic atrophy (Opa1)." (PMID 40428407, 2025). "Clinically, the presentation of SPG7-associated DOA resembles other etiologies of optic atrophy, such as DOA from OPA1 or optic atrophy from Wolfram syndrome." (PMID 41149856, 2025). "The large majority of these variants affected the AAA (ATPase) domain, suggesting that the unbalanced processing of OPA1 consequent to AFG3L2 dysfunction possibly leads to the optic atrophy phenotype." (PMID 39564550, 2024). "Similar to our results, under pathological conditions, OPA1 has been well studied in dominantly inherited optic atrophy." (PMID 36980838, 2023). "As its name indicates, optic atrophy is the hereditary disorder that has led to the identification of the OPA1 gene in humans." (PMID 37872238, 2023). "Application of the HITL-TAP analysis and subsequent unbiased PCA revealed that an optic atrophy-related gene OPA1 regulates the balance between tubular and lamellar cristae of mitochondria." (PMID 37651352, 2023). "Neurological symptoms due to myopathy and peripheral neuropathy were frequently investigated and treated in patients with OPA1 and TWNK mutations despite their features of optic atrophy, ptosis and ophthalmoplegia constituting the predominant phenotype." (PMID 37246228, 2023). "Mutations in MFN2 and OPA1 cause MDDS, presenting as optic atrophy, myopathy, axonal neuropathy and Charcot–Marie–Tooth disease in the case of MFN2 and optic atrophy and Behr syndrome in the case of OPA1." (PMID 34208592, 2021). "In contrast, the recessive variants identified in SPG7 (8.47%), OPA1 (5.08%), and SLC25A46 (1.69%) were associated with syndromic optic atrophies." (PMID 33841295, 2021). "Dendritic degeneration has been also documented in RGCs of AD mouse model, and there are other disease models such as OPA1-related optic atrophy in which dendrites are the primary site of pathology." (PMID 32848556, 2020). "Results from lines derived from the patient with syndromic OPA1 parkinsonism are denoted as Opa1P, whereas lines derived from the patient with optic atrophy are represented as Opa1." (PMID 29604226, 2018). "Microsatellite study performed for family A and B revealed segregation to OPA1, the major optic atrophy locus." (PMID 28841713, 2017). "The visual deficits in individuals affected by these forms of hereditary optic atrophies involving mutations in either mtDNA, as in LHON, or in nuclear genes (OPA1 and OPA3) encoding for mitochondrial membrane proteins mitochondrial membrane proteins." (PMID 28081242, 2017). "Optic atrophy is the defining feature of DOA, but a specific missense mutation within the OPA1 gene, c.1334G >A (p.Arg455His), has been consistently associated with sensorineural deafness in a number of families." (PMID 27696015, 2016).